SCN2A (sodium voltage-gated channel alpha subunit 2)
Diseases named in the same sentence as SCN2A in open-access papers (continued):
Sharing a sentence is not in itself a finding about the gene and the disease.
Intellectual disability (49 papers, 2015 to 2026). "Both typically lead to severe phenotypes, including profound intellectual disability and intractable epilepsy due to the loss of function in the SCN2A protein." (PMID 40507552, 2025). "This systematic review aims to identify specific SCN2A variants, including novel mutations, and correlate them with neurological and developmental phenotypes such as seizures, intellectual disability, and motor impairments." (PMID 40507552, 2025). "Variants of SCN2A are frequently associated with autism spectrum disorder and intellectual disability, in addition to infantile seizures." (PMID 37240836, 2023). "Mutations in genes associated with synaptic signaling/neurotransmission, including mutations in SCN2A, the gene encoding the sodium channel Nav1.2, have also been identified in patients with intellectual disability and ASD21." (PMID 35365720, 2022). "Here, we present a case of a 12-year-old girl with nonsyndromic intellectual disability who exhibited a heterozygous de novo missense mutation in SCN2A." (PMID 30062040, 2018). "Our group also identified a SCN2A mutation in a patient with infantile spasm and severe intellectual disability previously." (PMID 25951140, 2015). "Dysfunction in the gene SCN2A, which encodes the voltage-gated sodium channel Nav1.2, is strongly associated with neurodevelopmental disorders including autism spectrum disorder and intellectual disability (ASD/ID)." (PMID 38151324, 2023). "Such conditions could mimic cases of SCN2A haploinsufficiency, associated with autism spectrum disorder and intellectual disability." (PMID 34425903, 2021). "Combined, these results suggest that common variation in SCN2A plays a role in cognitive ability, which may explain why mutations in SCN2A often cause intellectual disability." (PMID 32264956, 2020). "Here we demonstrated ethosuximide-sensitive absence-like seizures with bilateral SWDs in mice heterozygous for a patient-derived Scn2a-RX nonsense knock-in mutation originally described in a patient with epileptic encephalopathy, intellectual disability, and ASD4." (PMID 30175250, 2018). "Examples include SCN2A, IQSEC2, and ADSL, whose mutations are associated with seizures, motor delays, and severe intellectual disability." (PMID 41300846, 2025). "While ASD has been traditionally considered a polygenic disorder, recent large-scale human genetic studies have identified SCN2A deficiency as a leading monogenic cause of ASD and intellectual disability." (PMID 37841865, 2023). "The heterozygous deletion of SCN2A mainly induces autism spectrum disorders and intellectual disability." (PMID 35819063, 2022). "The broader developmental dysfunction phenotypes observed in SCN2A syndromes may also serve as a model to aid our understanding of developmental dysfunction in other neurodevelopmental disorders with which it is genetically linked, such as intellectual disability and schizophrenia." (PMID 32264956, 2020). "In recent years, SCN2A has been recognized as one of the most frequently mutated genes in neurodevelopmental disorders including autism spectrum disorders (ASD), intellectual disability (ID), developmental and epileptic encephalopathy (DEE) and schizophrenia." (PMID 30813884, 2019). "By analyzing data from 695 patients across 11 studies, the findings highlight the prevalence of SCN2A mutations in ASD and their significant contribution to diverse neurological symptoms, including seizures, intellectual disability, motor impairments, and behavioral deficits." (PMID 40507552, 2025).
Intellectual disability (continued). "Frameshift mutations have been noted in SCN2A in children having intellectual disability (ID) without seizure history." (PMID 33841294, 2021). "This can be particularly useful when different variant consequences are associated with different syndromes (e.g., SCN2A, where loss of function variants are associated with nonspecific severe intellectual disability, and missense variants with infantile epileptic encephalopathy)." (PMID 35143074, 2022). "Pathogenic variants in SCN2A are reported in a spectrum of neurodevelopmental disorders including developmental and epileptic encephalopathies, benign familial neonatal-infantile seizures, episodic ataxia, and autism spectrum disorder and intellectual disability with and without seizures." (PMID 35794776, 2023). "Recently, SCN2A has been reported as a gene responsible for nonsyndromic intellectual disability or autism spectrum disorders." (PMID 30062040, 2018). "In addition, whether mice heterozygous for Scn2a display behavioral phenotypes related to ASD and intellectual disability remains unclear." (PMID 31249508, 2019).
Epileptic encephalopathy (47 papers, 2015 to 2026). A condition in which epileptiform abnormalities are believed to contribute to the progressive disturbance in cerebral function. "Pathogenically, SCN2A variants alter voltage-gated sodium channel activity, leading to early infantile epileptic encephalopathy, whereas PAH and GNPAT variants disrupt amino acid and peroxisomal metabolism, respectively." (PMID 41300846, 2025). "SCN2A variants are associated with a range of disorders including autism spectrum disorder, developmental delay, seizures, and epileptic encephalopathy." (PMID 39228919, 2024). "She showed delayed development after seizure control and ataxia later in life, which is consistent with the diagnosis of early-onset epileptic encephalopathy due to variants in SCN2A gene." (PMID 37152433, 2023). "SCN2A mutation has been reported in two Saudi girls who presented with early infantile epileptic encephalopathy starting in the first few days of life." (PMID 37628333, 2023). "We present genetic, clinical, electroencephalographic, and behavioral features of a 4-year-old girl with epileptic encephalopathy related to a de novo intronic variant in the SCN2A gene." (PMID 35711923, 2022). "Three recently characterized epileptic encephalopathy-associated variants in SCN2A—T236S, E999K, and S1336Y—all exhibit more pronounced alterations in their electrophysiological properties in 5N NaV1.2 isoforms compared to 5A isoforms." (PMID 34425903, 2021). "An anecdotal case with a de novo SCN2A splice site mutation associated with epileptic encephalopathy, early onset global developmental delay, intermittent ataxia, autism, hypotonia, and cerebral/cerebellar atrophy was recently reported." (PMID 28082152, 2018). "Based on these criteria, SCN2A—commonly linked to epileptic encephalopathy—has the highest level of evidence supporting its role in ASD." (PMID 28649286, 2017). "In some cases, genetic diagnosis modifies the treatment plan, like in a female who presented with neonatal epileptic encephalopathy, and we identified a de novo variant in the SCN2A gene which resulted in modifying the therapy to a ketogenic diet with good response." (PMID 37628333, 2023). "For example, the gain-of-function T226M mutation in Scn1a has been found in children with developmental and epileptic encephalopathy and gain-of-function mutations in Scn2a have been shown to elicit seizures, behavioral arrest, and behavioral abnormalities in mice." (PMID 35165201, 2022). "In addition, mutations in SCN2A also cause epileptic encephalopathy (MIM 613721) and missense variants in SCN3A have been implicated in focal epilepsy in children." (PMID 31694722, 2019). "Direct comparisons with knock-in mice bearing Scn2a missense mutations found in patients with early-infantile epileptic encephalopathies under the control of intrinsic Scn2a promoters may provide a more accurate model." (PMID 30175250, 2018). "Subsequently, we and others reported a number of de novo SCN2A mutations in patients with neurological disorders such as epileptic encephalopathy including Ohtahara syndrome, West syndrome, Lennox Gastaut syndrome, ASD10,11, intellectual disability, and schizophrenia." (PMID 30175250, 2018). "Theoretically, this approach could benefit individuals with both loss-of-function (protein-truncating variants, missense, splice site) and severe gain-of-function (missense) variants and at least eight cases of epileptic encephalopathy have been identified with variants in 5A of SCN2A or SCN8A." (PMID 34425903, 2021).
Epileptic encephalopathy (continued). "Mutations of the SCN2A gene, encoding the voltage gated sodium channel NaV1.2, have been associated to a wide spectrum of epileptic disorders ranging from benign familial neonatal-infantile seizures to early onset epileptic encephalopathies such as Ohtahara syndrome." (PMID 31501495, 2019). "Administration of an antisense oligonuceotide in a preterm infant with severe early-onset SCN2A developmental and epileptic encephalopathy was well tolerated and led to a 60% decrease in seizure frequency." (PMID 40263630, 2025). "Several reports have described SCN2A-related epileptic encephalopathy with severe cortical dysplasia and opercular malformation detected on MRI, as well as SCN3A variants linked to extensive cortical folding abnormalities." (PMID 41573391, 2025). "Febrile-associated epileptic encephalopathy is a large genetically heterogeneous group that is associated with pathogenic variants in SCN1A, PCDH19, SCN2A, SCN8A, and other genes." (PMID 35711923, 2022). "SCN2A and SCN8A mutations have been reported in some patients with severe epileptic encephalopathies." (PMID 33841294, 2021). "Among them are SCN2A or SCN3A, sodium channel encoding genes, strongly associated with epileptic encephalopathy." (PMID 33126574, 2020). "Both severe epileptic encephalopathy and self-limited epilepsies were associated with KCNQ2 and SCN2A variants." (PMID 31572294, 2019). "Pathogenic variants in the SCN2A gene that produce loss-of-function of the protein lead to ASD/ID and increased channel activity that lead to epileptic encephalopathy early infantile 11 (EEIE11) and benign familial neonatal-infantile seizures (BFIS)." (PMID 31409060, 2019). "Mutations in SCN2A and more recently SCN3A are established monogenic causes of epileptic encephalopathy that, like SCN1A, cause dysfunction of the encoded ion-channels, which is believed to disturb the fine balance between neuronal excitation and inhibition." (PMID 30531953, 2018). "SCN2A (Nav1.2) and SCN8A (Nav1.6) mutations are found in patients with early infantile epileptic encephalopathy." (PMID 28536506, 2017). "Overall, the data is convincing that SCN2A leads to neurodevelopmental dysfunction other than epileptic encephalopathy." (PMID 28649286, 2017). "Here we describe the clinical experience with intrathecally administered elsunersen, a gapmer antisense oligonucleotide targeting SCN2A, in a female preterm infant with early-onset SCN2A developmental and epileptic encephalopathy, in an expanded access program." (PMID 40263630, 2025). "SCN2A variants, mostly truncations, are associated with autism and intellectual disability, as well as epileptic encephalopathies, while SCN8A variants cause developmental and epileptic encephalopathies with motor symptoms." (PMID 41010287, 2025). "The main diagnosis of children with SCN1A variants was Dravet syndrome (DS) (72.7%), whereas patients with SCN2A and SCN8A variants were mainly diagnosed with various types of epileptic encephalopathy, accounting for 85.7% (12 of 14) and 88.9% (8 of 9) respectively." (PMID 38174099, 2023). "Therefore, our findings regarding these genes are consistent with those of previous studies and confirm that patients with epileptic encephalopathy with SCN1A and SCN2A mutations respond well to KD, while patients with CDKL5 mutations respond poorly to KD." (PMID 30061856, 2018). "Sodium channel blockers have shown significant effectiveness in SCN2A-epileptic encephalopathies." (PMID 28082152, 2018). "Both deletions and duplications, involving each of SCN1A, SCN2A, and SCN3A, have been presented previously in cases with severe epileptic encephalopathies and developmental delay." (PMID 31694722, 2019).
Epileptic encephalopathy (continued). "These clinical features during the neonatal period were essentially nondistinguishable from those in early infantile epileptic encephalopathy due to KCNQ2 and SCN2A mutations." (PMID 31675180, 2019). "Disruptions in other ion channel genes, including SCN2A and SCN8A, may also result in epileptic encephalopathy and developmental regression before emergence of ASD symptoms." (PMID 28649286, 2017).
autism spectrum disorder (41 papers, 2014 to 2025). A spectrum of developmental disorders that includes autism, and Asperger syndrome. "Loss-of-function (LOF) mutations to the SCN2A gene, encoding Nav1.2, are associated with increased rates of autism spectrum disorder." (PMID 41010287, 2025). "SCN2A is also a high-confidence risk gene for autism spectrum disorder (ASD) and nonsyndromic intellectual disability (ID)." (PMID 37578743, 2023). "SCN2A, encoding the neuronal voltage-gated Na+ channel NaV1.2, is one of the most commonly affected loci linked to autism spectrum disorders (ASDs)." (PMID 34156984, 2021). "SCN2A is an autism spectrum disorder (ASD) risk gene and encodes a voltage-gated sodium channel." (PMID 38293651, 2023). "Recently, de novo SCN2A mutations in autism spectrum disorder (ASD) have been identified." (PMID 24650168, 2014). "Two highly penetrant autism spectrum disorder genes, SCN2A and SHANK3, are represented among the top 20 genes with the highest number of DNMs." (PMID 38395944, 2024). "More recently, loss-of-function SCN2A mutations have also been identified in patients with autism spectrum disorder (ASD) without overt epileptic phenotypes." (PMID 31501495, 2019). "The SCN2A gene can cause a wide array of phenotypes ranging from benign familial neonatal infantile seizures (BFIS) and developmental and epileptic encephalopathy (DEE) to neurodevelopmental disorders such as autism spectrum disorder (ASD) and intellectual disorder (ID)." (PMID 34093402, 2021). "Previous studies report a potential susceptibility region at the chromosomal locus 2q including SCN1A, SCN2A and SCN3A genes for autism spectrum disorder (ASD)." (PMID 30071822, 2018).
Dravet syndrome (26 papers, 2013 to 2026). "Different from SCN1A LOF variants, SCN2A GOF variants can also cause Dravet syndrome, and oxcarbazepine treatment is usually effective." (PMID 37152433, 2023). "This was also confirmed by the different phenotypes in the family of Patient 48, ranging from normal to Dravet syndrome in the carriers of the same SCN2A variant." (PMID 35431799, 2022). "By clinical exome sequencing, we identified two novel mutations: c.4973C>A (p.Thr1658Lys) in SCN1A gene and c.1283A>G (p.Tyr428Cys) in the SCN2A gene, whereas the third mutation c.3295G>T (p.Glu1099*) was already described in patients with Dravet syndrome." (PMID 31439038, 2019). "For instance, the Othahara syndrome could be due to mutations in the KCNQ2 and SCN2A genes and the Dravet Syndrome could be due to mutations in the SCN1A, SCN2A, SCN1B genes." (PMID 31907053, 2020). "The variant c.A2851G (p.M951V) in SCN2A occurred close to the selectivity filter, paralogous to SCN1A variants observed in Dravet Syndrome." (PMID 32666661, 2020). "Previous studies have shown that patients with Dravet syndrome with SCN1A mutations respond well to KD, as did a patient with an SCN2A mutation who was treated with a modified Atkins diet." (PMID 30061856, 2018). "On the other hand, Dravet's Syndrome is reported to have mutations in SCN1A, SCN2A, and SCN1B, and the mutations in both SCN1A and SCN2A lead to GEFS+." (PMID 23662118, 2013). "Both SCN2A and SCN1A variants are responsible for Dravet syndrome." (PMID 37152433, 2023). "Besides the six patients with SCN1A variants who could all be classified as having Dravet syndrome, large phenotypic heterogeneity was noted among patients with PRRT2, KCNQ2, and SCN2A variants." (PMID 31572294, 2019).